FOXP1 (forkhead box P1)
Diseases named in the same sentence as FOXP1 in open-access papers (continued):
Sharing a sentence is not in itself a finding about the gene and the disease.
prostate tumors (2 papers, 2015 to 2017). "It is unknown whether this region has a tumor suppressive function, but more than 12% of primary prostate tumors show copy number loss of the 3p13-14 region from FOXP1 to SHQ1 (termed FOXP1-SHQ1 deletion) and 15% show copy number loss of the individual FOXP1 or SHQ1 genes that bound the deletion." (PMID 29057879, 2017). "Consistent with MEK involvement, genes repressed by MEK activation are under-represented in prostate tumors from Foxp1-Shq1f/f;Ptenf/f mice relative to Ptenf/f mice at 12 months, as assessed by GSEA of RNA-seq expression data (P = 0.004, FDR = 0.05, GSEA)." (PMID 29057879, 2017). "The fact that all the prostate tumors are enriched for deletion of the entire locus or for deletion of both FoxP1 and Shq1, rather than selective deletion of FoxP1 and/or Shq1 individually, suggests that at least two genes in the interval play a role in restraining tumor progression in this model." (PMID 29057879, 2017).
serous adenocarcinoma (2 papers, 2022 to 2023). An adenocarcinoma that is characterized by the presence of papillary patterns and cellular budding. "Clear cell carcinoma patients were found to express FOXP1 mRNAmore than the serous carcinoma patients." (PMID 37546627, 2023).
Speech apraxia (2 papers, 2022 to 2023). A type of apraxia that is characterized by difficulty or inability to execute speech movements because of problems with coordination and motor problems, leading to incorrect articulation. "In contrast, a P215A substitution within the FOXP1 Q-rich region was deemed unlikely to underlie developmental verbal dyspraxia (DVD)." (PMID 37507770, 2023).
speech disorder (2 papers, 2019 to 2025). A term referring to disorders characterized by the disruption of normal speech. "ADHD and DLD share genetic risk loci, including FOXP1 and FOXP2, with rare variants associated with both speech disorders and ADHD." (PMID 41009966, 2025).
Splenomegaly (2 papers, 2019 to 2025). Abnormal increased size of the spleen. "Given that rTreg cells function as suppressors of lymphoproliferation, the reduced rTreg cell number may explain the early splenomegaly and lymphadenopathy in young Foxp1-deficient mice." (PMID 31125332, 2019). "Treg-specific deletion of both FOXP1 and FOXP4 in cDKO mice resulted in splenomegaly and peripheral lymph node (pLN) enlargement." (PMID 40794436, 2025).
viral infection (2 papers, 2020 to 2024). "As summarized in this review, Tfh cell-related transcription factors including Bcl6, IRF4, STAT1/STAT4/STAT5, T-bet, TCF-1, LEF-1, TOX2, Bach2, FOXP1, and KLF2 are all involved in the virus infection." (PMID 32766317, 2020). "FOXP1 (pluripotent transcription factor, including regulation of endothelial activation) was elevated in viral infection in comparison with bacterial infection and KD but not MIS-C." (PMID 39300098, 2024).
anorexia nervosa (1 paper, 2016). A disorder most often seen in adolescent females characterized by a refusal to maintain a minimally normal body weight, an intense fear of gaining weight, a disturbance in body image, and, in postmenarcheal females, the development of amenorrhea. "Of those nine genes, AKAP6 and NTNG1 were genes associated with anorexia nervosa and the remaining seven (AGT, CD36, CD38, FOXP1, PPARA, PPARG and SELL) were selected for their relationship with T2D." (PMID 27483138, 2016).
autoimmune hemolytic anemia (1 paper, 2025). Autoimmune hemolytic anemia (AIHA) is an autoimmune disorder in which various types of auto-antibodies are directed against red blood cells causing their survival to be shortened and resulting in hemolytic anemia. "cDKO mice also had detectable serum anti–red blood cell (RBC) antibodies, whereas no RBC-specific antibodies were detected in >500-day-old CrePos mice, suggesting FOXP1- and FOXP4-deficient Tregs develop lethal autoimmune hemolytic anemia (AIHA)." (PMID 40794436, 2025).
B-cell neoplasm (1 paper, 2014). A group of heterogeneous lymphoid tumors generally expressing one or more B-cell antigens or representing malignant transformations of B-lymphocytes. "In contrast, non-IG rearrangements of FOXP1 are found as secondary genetic hits acquired during clinical course of various B-cell neoplasms (DLBCL, MZL and CLL), frequently heralding inferior outcome." (PMID 24416450, 2014).
behavioral disorders (1 paper, 2023). "The forkhead box protein P1 (FOXP1) gene has been associated with behavioral disorders." (PMID 36923289, 2023).
Blindness (1 paper, 2022). Blindness is the condition of lacking visual perception defined as a profound reduction in visual perception. "As AMD is the primary cause of blindness among the elderly, this study aimed to investigate the roles of Foxp1 in CNV by eye-selective deletion of Foxp1." (PMID 35248156, 2022).
brain ischemia (1 paper, 2026). Diminished or absent blood supply to the brain caused by obstruction (thrombosis or embolism) of an artery resulting in neurologic damage. "Emerging evidence suggests that FOXP1 suppresses NLRP3 inflammasome activation, mitigating brain ischemia–reperfusion injury." (PMID 41596522, 2026).
cardioembolic stroke (1 paper, 2020). "FOXP1 was significantly more than twofold upregulated in the PBMC of MS (P = 2.35E-09, logFC = 1.21) and significantly 1.3-fold upregulated in the blood cells of cardioembolic stroke (p = 1.55E-05, logFC = 0.34)." (PMID 32719717, 2020).
Cerebellar hypoplasia (1 paper, 2022). Cerebellar hypoplasia is a descriptive term implying a cerebellum with a reduced volume, but a normal shape and is stable over time. "Recently, a large exome sequencing study of children and adults with DWM and cerebellar hypoplasia expanded the list of genes associated with DWM to include TUBA1A, BRAF, SETD2, FOXP1, PUS3, ARMC9, and PIBF1." (PMID 35202430, 2022).
cerebral palsy (1 paper, 2024). A group of disorders affecting the development of movement and posture, often accompanied by disturbances of sensation, perception, cognition, and behavior. "Another heterozygous likely pathogenic variant was identified in the splice region of gene FOXP1 (c.1723-2A>C), in a single patient with clubfoot, cerebral palsy, lower limb hypotrophy, and horizontal nystagmus that was cognitively challenged." (PMID 38929227, 2024).
choanal atresia (1 paper, 2023). Choanal atresia (CA) is a congenital anomaly of the posterior nasal airway characterized by the obstruction of one (unilateral) or both (bilateral) choanal aperture(s), with clinical manifestations ranging from acute respiratory distress to chronic nasal obstruction. "The present subject also has right choanal atresia and facial asymmetry, which have never been described in the FOXP1-related ID syndrome." (PMID 37521304, 2023).
choroidal neovascularization (1 paper, 2022). An eye disorder described by the growth of new blood vessels that originate from the choroid through a break in the Bruch membrane into the sub–retinal pigment epithelium (sub-RPE) or subretinal space. "In this study, we aimed to determine whether loss of Foxp1 affects laser-induced choroidal neovascularization (CNV) in mouse." (PMID 35248156, 2022).
chronic lung disease (1 paper, 2022). According to the definitions of the American and British Thoracic Societies, including pulmonary functional tests, X-rays, and CT scans for items such as fibrosis, bronchiectasis, bullae, emphysema, nodular or lymphomatous abnormalities. "Overall, these data suggested that loss of FoxP1 may contribute to the development of chronic lung diseases because variants in the FoxP1 gene that were associated with higher mRNA levels were also associated with improved lung function and reduced odds of a diagnosis of IPF." (PMID 36221131, 2022). "Therefore, our findings implicate the FoxP1 gene as a protective mediator against chronic lung diseases such as COPD and IPF." (PMID 36221131, 2022).
chronic obstructive pulmonary disease (1 paper, 2017). A chronic and progressive lung disorder characterized by the loss of elasticity of the bronchial tree and the air sacs, destruction of the air sacs wall, thickening of the bronchial wall, and mucous accumulation in the bronchial tree. "In another study, gene expression profiling of PBMCs obtained from smokers exhibited a signature of chronic obstructive pulmonary disease (COPD) and emphysema characterized by multiple differentially regulation of genes FOXP1, TCF7, and ASAH1 involved in sphingolipid (ceramide) metabolism." (PMID 29376056, 2017).
clubfoot (1 paper, 2024). The most common congenital deformation of the foot, occurring in 1 of 1,000 live births. "The clinical presentation of FOXP1 syndrome includes a wide range of symptoms, such as neurodevelopmental and syndromic clubfoot, which could be a rare feature of this disorder in our patient." (PMID 38929227, 2024).
diabetic retinopathy (1 paper, 2025). "We discovered a significant three-way interaction among ABCA4_rs17110929, MMP2-AS1_rs2576531, and FOXP1_rs557869288 that substantially increases diabetic retinopathy susceptibility through complementary mechanisms, affecting retinal homeostasis." (PMID 41010507, 2025). "This study advances our understanding of diabetic retinopathy pathogenesis by identifying novel genetic variants (ABCA4_rs17110929, MMP2-AS1_rs2576531, FOXP1_rs557869288) and additional loci (MRPS33_rs1533933, DRD2_rs4936270)." (PMID 41010507, 2025). "We proposed a synergistic mechanism of ABCA4/MMP2-AS1/FOXP1 in diabetic retinopathy." (PMID 41010507, 2025). "As a negative regulator of pathological angiogenesis, FOXP1 dysfunction would dysregulate angiogenic responses critical in diabetic retinopathy, leading to unopposed VEGF signaling and aberrant neovascularization characteristic of proliferative diabetic retinopathy (PDR)." (PMID 41010507, 2025).
familial breast cancer (1 paper, 2018). "Previous studies have demonstrated that loss of FOXP1 expression is associated with a poor prognosis in primary invasive and familial breast cancer." (PMID 29848352, 2018).
fatty liver disease (1 paper, 2023). A reversible condition wherein large vacuoles of triglyceride fat accumulate in liver cells via the process of steatosis. "A study showed that exosomes transferring miR-107 targeted the regulation of Foxp1 in clusters of differentiation 4 positive T (CD4+T) cells for the development of fatty liver disease." (PMID 37600712, 2023).
glaucoma (1 paper, 2025). Increased pressure in the eyeball due to obstruction of the outflow of aqueous humor. "The broad developmental expression of FOXP4 and its role in anterior segment disease also warrant further studies exploring the links between other FOXP transcription factors, such as dimerization partners FOXP1 and FOXP2, in glaucoma and ASD." (PMID 40637512, 2025).
hearing loss (1 paper, 2024). "Meanwhile, FOXP1 was only detected in DD/ID with malformation group, and ASXL3 was most frequently involved in DD/ID with hearing loss group." (PMID 38649797, 2024).
hemorrhage (1 paper, 2024). Loss of blood from the vascular compartment to the exterior or into nonvascular body space as a result of rupture or severance of the blood vessels. "Knockdown of Foxp1 in ECs in culture inhibits EC proliferation, migration, and tube formation, while constitutive Foxp1 knockout mice die at E14.5 with complex cardiovascular defects including vascular hemorrhage." (PMID 36795082, 2024).
Hernia (1 paper, 2022). "Evidence for shared susceptibility was further provided at nine loci including 2p21 (THADA), 3p14.3 (ERC2), 3p13 FOXP1, 4q34.1 (HAND-AS1), 5p15.33 (CEP72), 7p15.2 (LOC646588), 7q33 (CALD1) and 9q22.31 (BARX1) of which eight were previously discovered on individual hernia GWAS analyses." (PMID 36584111, 2022).
Hydrocephalus (1 paper, 2025). Hydrocephalus is an active distension of the ventricular system of the brain resulting from inadequate passage of CSF from its point of production within the cerebral ventricles to its point of absorption into the systemic circulation. "As mildly enlarged lateral ventricles, known as hydrocephalus e vacuo, have been observed in some individuals with FOXP1 syndrome, this raises the question of whether neuroinflammation in FOXP1 haploinsufficiency can lead to striatal neurodegeneration." (PMID 40568906, 2025).
hydronephrosis (1 paper, 2021). Collection of urine in the renal pelvis that results in dilatation of the renal pelvis and calyces. "This is consistent with findings from Bekheirnia and colleagues which described eight unrelated individuals with de novo mutations in FOXP1; four had genitourinary abnormalities, including unilateral renal agenesis, hydronephrosis, hypospadias, and a duplicated renal collecting system." (PMID 33892622, 2021).
hypereosinophilic syndrome (1 paper, 2022). Hypereosinophilic syndrome (HES) constitutes a rare and heterogeneous group of disorders, defined as persistent and marked blood eosinophilia and/or tissue eosinophilia associated with a wide range of clinical manifestations reflecting eosinophil-induced tissue/organ damage. "Early evidence of FOXP1 role in T-cells came from a study of lymphocytic variant of hypereosinophilic syndrome (L-HES) patients." (PMID 36268015, 2022).
Hypertonia (1 paper, 2012). A condition in which there is increased muscle tone so that arms or legs, for example, are stiff and difficult to move. "The first hint that FOXP1 may be involved in neurodevelopmental disorders was provided by a heterozygous deletion in 3p14.1, which affected FOXP1, EIF4E3, PROK2 and GPR27, in a patient with speech delay, hypertonia and additional phenotypes." (PMID 22736078, 2012).
inflammatory bowel disease (1 paper, 2020). A spectrum of small and large bowel inflammatory diseases of unknown etiology. "The aberrant expression of IL10 and FOXP1 was associated with various immune‐mediated inflammatory diseases, including RA, SLE and inflammatory bowel disease, and the importance of IL‐10 in immune regulation for AIH has been recognized." (PMID 32808463, 2020).
insomnia (1 paper, 2026). A sleep disorder characterized by difficulty in falling asleep and/or remaining asleep. "Here, we report that individuals with FOXP1 syndrome suffer from insomnia with sleep maintenance problems and early waking." (PMID 41919501, 2026).
intestinal inflammation (1 paper, 2018). "Furthermore, Treg-specific deletion of Foxp1 resulted in significantly reduced Nrp1−Helios− iTreg population, which was phenotypically reflected in enhanced age-related and DSS-induced intestinal inflammation in these mice." (PMID 30367168, 2018).
invasive carcinoma (1 paper, 2017). A carcinoma that is not confined to the epithelium, and has spread to the surrounding stroma. "Histologic features of the Foxp1-Shq1f/f;Ptenf/f tumors ranged from invasive carcinoma consisting of a well-differentiated glandular component transitioning to a poorly differentiated epithelial component with sheet-like architecture at 9 months." (PMID 29057879, 2017).
Langerhans cell histiocytosis (1 paper, 2025). Langerhans cell histiocytosis (LCH) is a systemic disease associated with the proliferation and accumulation (usually in granulomas) of Langerhans cells in various tissues. "FOXP1 expression showed a positive correlation with the cytolytic score in AML, MM, Langerhans cell histiocytosis (LCH), and chronic myeloid leukemia (CML)." (PMID 40672953, 2025).
liver cirrhosis (1 paper, 2016). "FOXP1 expression was remarkably correlated with HBV infection (p = 0.0123) and liver cirrhosis (p = 0.0008)." (PMID 27618020, 2016).
liver fibrosis (1 paper, 2024). "Moreover, PA-induced hepatocytes secrete miR-107-enriched EVs, which activate HSCs by suppressing dickkopf-1 (DDK1) and Th9 cell differentiation by mediating Forkhead box protein P1 (Foxp1), exacerbating MASH-related liver fibrosis." (PMID 39396032, 2024).
lymph node metastasis (1 paper, 2024). "The positive rates of FOXP1 were significantly lower in patients with poor differentiation, lymph node metastasis, invasion into surrounding organs, and advanced stages (p < 0.05)." (PMID 38279090, 2024). "FOXP1 expression was also negatively correlated with lymph node metastasis (p < 0.01)." (PMID 38279090, 2024). "Patients with negative FOXP1 expression are usually characterized by aggressive features such as advanced stages, poor differentiation, and lymph node metastasis." (PMID 38279090, 2024). "Moreover, Cox multivariate analysis showed that negative FOXP1 expression, advanced TNM stages, invasion, and lymph node metastasis were independent prognostic risk factors in patients with ICC." (PMID 38279090, 2024).
lymphoproliferative disorder (1 paper, 2018). "Taken together, these results revealed that Treg-specific deletion of Foxp1 is moderately associated with lymphoproliferative disorder and age-associated inflammation at mucosal sites, a major cause of which can be attributed to impaired iTreg homeostasis." (PMID 30367168, 2018).
macrosomia (1 paper, 2018). "However, some of the additional clinical features noted in our patients such as the skeletal anomalies and fevers in patient one and the macrosomia in patient three have not been previously reported in patients with FOXP1 mutations." (PMID 30385778, 2018).
male infertility (1 paper, 2016). The inability of the male to effect fertilization of an ovum after a specified period of unprotected intercourse. "Validation of class II high-impact variants within SPATA31E1, OVGP1, FOXP1, FBXO43 indicate further putative loci for stallion fertility, however the consequences of mutations on male infertility in human and mice are not yet known." (PMID 27079378, 2016).
muscular atrophy (1 paper, 2021). The loss of muscle tissue due to inactivity or disease. "Indeed, an animal study with Foxp1+/− mice reflecting FOXP1 haploinsufficiency found pronounced muscular atrophy in the esophagus and colon, caused by reduced muscle cell proliferation and associated dysregulation of genes implicated in smooth and skeletal muscle morphogenesis and function." (PMID 34588003, 2021).
muscular dystrophy (1 paper, 2024). Muscular dystrophy (MD) refers to a group of more than 30 genetic diseases characterized by progressive weakness and degeneration of the skeletal muscles that control movement. "In addition, we also attempted to mimic the Duchenne muscular dystrophy (Dmd) gene and ***Fork-head Box P subfamily 1 (Foxp1) gene mutant mice." (PMID 38280977, 2024).
myocardial ischemia (1 paper, 2022). A disorder of cardiac function caused by insufficient blood flow to the muscle tissue of the heart. "The specific mechanism by which FoxP1 regulating angiogenesis during myocardial ischemia has not yet been researched." (PMID 36088337, 2022).
Noonan syndrome (1 paper, 2018). Noonan Syndrome (NS) is characterized by short stature, typical facial dysmorphism and congenital heart defects. "Four patients who carried LGD variants in known DD genes (POGZ, ARID1B, FOXP1, and SIN3A) and one patient who carried a known activating variant in the Noonan syndrome gene PTPN11 were considered pathogenic variants by the American College of Medical Genetics and Genomics guidelines." (PMID 30532227, 2018).
pancreatic adenocarcinoma (1 paper, 2025). "We first examined the expression of FOXP1 in pancreatic adenocarcinoma (PAAD) using The Cancer Genome Atlas (TCGA) data from the GEPIA2 dataset." (PMID 40169859, 2025).
pancreatic ductal adenocarcinoma (1 paper, 2024). An infiltrating adenocarcinoma that arises from the epithelial cells of the pancreas. "For instance, FOXP1 expression was significantly downregulated in the pancreatic ductal adenocarcinoma compared to that in the adjacent tissues, and a negative FOXP1 expression was associated with poor differentiation, lymph node metastasis, invasion of adjacent tissues, and a poor prognosis." (PMID 38279090, 2024).